CD68 (CD68 molecule)
Diseases named in the same sentence as CD68 in open-access papers (continued):
Sharing a sentence is not in itself a finding about the gene and the disease.
tumor (continued). "Immunohistochemistry primarily aids in excluding other lineages, with tumor cells typically showing strong vimentin expression and cytoplasmic CD68 positivity (a histiocyte marker), while consistently negative for other lineage-specific markers, making UPS a diagnosis of exclusion." (PMID 41194829, 2025). "In addition, Cluster 7 was increased in WT tumours and corresponded to F4/80+ and CD68+ population, indicative of a more differentiated macrophage phenotype." (PMID 39746898, 2025). "Additionally, when calculating the intercellular distance, CD68+ macrophages were significantly enriched within 50 μM of panCK+ tumor cells in the responder group compared to the non‐responder group." (PMID 40995650, 2025). "To assess the PCa tumour microenvironment for impaired immunity, we also performed a pilot RNA-expression analysis for PCa-associated immunological factors (IL1β, IL10, IL18, TNF-α, TLR4, GATA3, CD68)." (PMID 40430084, 2025). "Additionally, CD68, a pan-macrophage marker, is often expressed by metastatic tumor cells to escape macrophage-mediated phagocytosis and the cytotoxic effects of CD8+ T cells." (PMID 40458726, 2025). "Quantification of Rep+CD68+ macrophages resembled quantification of Rep+ cells alone, and numbers were increased in tumor-distant (mean 5.6%) and peritumor (4.9%) tissues compared to tumor tissues (0.2%, p < 0.0001 and p < 0.001)." (PMID 40136704, 2025). "On these bases, we moved to large‐scale MIF analyses and stained 326 samples from 292 patients for the expression of CD8 (tumour infiltrating T cells), CD68 (tumour infiltrating monocyte/macrophages), cytokeratins (tumour cells), and nuclei, along with CD274 (PD‐L1)." (PMID 40545725, 2025). "CD68 (3.42 ± 1.16% of primary tumour was positive via IHC) immunoreactivity identified the presence of cells from the monocyte lineage, suggesting an accumulation of macrophages and osteoclasts within the OS tumour, particularly at the tumour-bone interface." (PMID 41315643, 2025). "Additionally, a higher number of CD68+ macrophages was detected in tumor-distant (25.6%) and peritumor tissue (25.2%) compared to tumor tissues (10.0%, p < 0.001 and p < 0.001)." (PMID 40136704, 2025). "In STAD, the M1-skewed (iNOS+) CD68+ population, despite PD-L1 co-localization, may retain anti-tumor activity through nitric oxide-mediated cytotoxicity, explaining the favorable prognosis." (PMID 40918116, 2025). "A recent study investigating the spatial distribution and density of immune cell populations in LMUM lesions highlights an enrichment of CD68 + and CD163 + M2-polarized tumor-associated macrophages (TAMs) — a cell type often associated with supporting a pro-tumor microenvironment." (PMID 41160198, 2025). "Given the critical role of CXCL9 as a T-cell attractant, effective anti-tumor response of CXCL9+CD68+ cells may necessitate their proximity to T cells." (PMID 39965007, 2025). "Tumors also contained numerous intermingling CD68+ and PDL1+ macrophages that were significantly elevated in lymphoid aggregates and the NOS2+ tumor edge, while COX2+ macrophages were associated with NOS2+ tumor edges when compared with the tumor core and/or tumor satellite regions." (PMID 40663402, 2025). "Similarly, in mIDH1 iCCA, the strongest interactions were between tumor cells and αSMA+ fibroblasts, as well as tumor cells and CD68+/CD163- macrophages." (PMID 39969434, 2025). "The IHC analysis of CD68+ TAM infiltration both in tumor and tumor-adjacent tissues showed a weak association with clinicopathological variables and BCR-free time, which may be a result of the limited sample size." (PMID 38189834, 2024). "Our spatial analysis revealed that only high effective density-CD68+SHP2+ TAMs in tumor region could predict poor OS." (PMID 38799432, 2024). "Higher expression of CD68 along with its lysosomal localization may in turn imply enhanced phagocytosis of tumor cells." (PMID 38287290, 2024).
tumor (continued). "Other immunohistochemical markers that may be focally positive and heterogeneous in tumor cells include desmin, CD68, vimentin, glypican‐3, and CD10, whereas myogenin, S‐100 protein, CD117, and HepPar 1 should be negative." (PMID 39587653, 2024). "An increase of CD68+ macrophages within the tumor has also been reported." (PMID 39635522, 2024). "The proportions of CD68+ SHP2+ TAMs (P < 0.05) were higher in tumor than in stroma." (PMID 38799432, 2024). "The total percentage of CD11b+F4/80+ tumor-associated macrophages (TAMs) did not change between the treatment groups, but the percentage of M1 (CD68+MHC-II+) macrophages was significantly increased in the ADU-S100 + anti-PD-L1 therapy cohort." (PMID 38312842, 2024). "On immunohistochemical analysis, these tumor cells were positive for CD68 and vimentin." (PMID 38515205, 2024). "Differences were statistically significant between tumoral LLT1 expression and stroma- and tumor-infiltrating CD68+ macrophages (Kruskal–Wallis test, p = 0.03 and p = 0.001, respectively), and also tumor-infiltrating CD163+ macrophages (Kruskal–Wallis test, p = 0.002)." (PMID 38673902, 2024). "Specifically, the CD3+PanCK+ and CD8+PanCK+ phenotypes identify T cells that are in close proximity with tumor cells, while the CD68+PanCK+ phenotype localizes CD68+ cells that are in close contact with tumor cells and the CD68+CD8+ phenotype recognizes T cells interacting with macrophages." (PMID 38605049, 2024). "The authors found that a high density of CD68 TAMs in the IT region was also associated with high AFP levels, large tumor size, absence of encapsulation, presence of vascular invasion and a higher tumor-node-metastasis (TNM) stage." (PMID 38997297, 2024). "Additionally, pancreatic cancer patients with a high density of CD68 + TAMs within the tumor stroma tend to exhibit significantly reduced overall survival rates." (PMID 38273373, 2024). "And the high infiltration of CD68+SHP2+ TAMs in tumor areas correlated with poor OS (P < 0.05)." (PMID 38799432, 2024). "Furthermore, the mRNA levels of the macrophage marker CD68 correlated weakly positively with the tumor volume." (PMID 39272860, 2024). "Type 1-polarized macrophages (M1), identified by the expression of CD80, CD86, MHC II, iNOS, and CD68, were phagocytic and could impede tumor progression." (PMID 39434887, 2024). "In addition, the CD206 expression of CD68+CD206+M2 TAMs closer to the tumor cells was lower, while the expression of CD163 and CD206 on TAMs was negatively correlated." (PMID 38279145, 2024). "Additionally, CD68 in the middle of the tumor exhibited moderately positive and significant correlations with CD163 at the margin (p value = 0.0003) and PD-L1 expression (p value = 0.0409)." (PMID 39338178, 2024). "In addition, in the TMA analyses, based on individual calculations of staining INT and POS, a higher Rep INT and POS in the tumor‐adjacent mucosa correlated with an increased CD68 INT and POS." (PMID 36811271, 2024). "In the tumor‐adjacent mucosa, congruent localization patterns of Rep and CD68 were observed." (PMID 36811271, 2024). "We observed that CCL18 was highly expressed in tumour-infiltrating CD68+ macrophages, which attracted Tregs via the CCL18/CCR8 interaction, so we speculated that CCL18+ macrophages could lead to the accumulation of CCR8+ Tregs in the TME." (PMID 37935468, 2024). "To further verify the localization of SENP3, we performed multiple immunofluorescence staining, and the results showed that SENP3 was significantly upregulated in CD68-positive cells in tumor tissues compared with normal tissues, which is a common marker of macrophages." (PMID 39123188, 2024). "The panel consisted of primary antibodies against various immune cells, including CD20+ B cells, CD3+ T cells, CD8+ T cells, CD68+ macrophages (Mø), CD163+ tumor-associated macrophages (TAMs), CD14+ monocytes (M), CD15+ neutrophils (NE), FOXP3+ Treg cells, and the proliferation marker Ki67." (PMID 38164148, 2024).
tumor (continued). "The overall CD68+ macrophage densities were higher in the first resected metastases compared to the re-metastasectomies; however, the difference was statistically significant only in the epithelial and overall compartments in the tumour centre." (PMID 38386105, 2024). "Similarly, pharmacologic inhibition of STAT3 or genetic depletion of CCL2 and CCL7 reduced pro-tumor CD45highCD11b+CD68+CD206+ macrophages in CT2A tumors." (PMID 38443336, 2024). "Blood vessel (CD31+) and TAM (CD68+) density were analysed in ten different patient samples for each of the three cancer types, always in five different microarray sections for each individual tumour specimen." (PMID 38589466, 2024). "Therefore, sections containing tumor and tumor-adjacent adipose tissue were stained with antibodies against CD68 and CD163 to detect M2-like polarized macrophages." (PMID 39456610, 2024). "To examine whether macrophage BMP signaling in the mBC bone TME affects patient survival, we performed survival analysis of patients with mBC who exhibited high versus low abundance of CD68+/pSMAD1-5-9+ macrophages in the tumor segments of mBC bone lesions." (PMID 38193534, 2024). "Next, immunostaining for AKT1 in paired tumor-free and tumor-containing lymph node specimens showed significantly higher co-localization of AKT1 with macrophages (marked by CD68) in the tumor-containing lymph node compared to the tumor-free lymph node from the same patient." (PMID 38719996, 2024). "Immunohistochemical results showed a significant increase in the infiltration of CD4+ T cells, CD8+ T cells, CD68+ macrophages, and F4/80+ Kuffer cells in tumor tissues, which suggested a high degree of immune infiltration in the tumor tissues of DEN and CCl4-induced HCC mouse models." (PMID 38580754, 2024). "Within the tumor center, CD68 counts were correlated with CD4, CD8, and CD163 of the same region." (PMID 39338178, 2024). "The group with low density had less than 268 CD68+ cells per mm2 of tumor stroma, the intermediate group had between 268 and 707, and the group with high density had above 707 CD68+ cells per mm2 of tumor stroma (maximum density was 7010 CD68+ cells per mm2)." (PMID 38407700, 2024). "By dividing macrophages into three distinct subpopulations based on CD68 and CD163 markers and known biology of tumor associated macrophages, we could assign them to different CNCs that reflect functional difference." (PMID 38575670, 2024). "While appropriate characterization of GAMM histological staining likely requires context-dependent interpretation (e.g., according to spatial analysis in the TME and by tumor subtype), many studies consistently reported increased CD68 after various forms of therapy." (PMID 39409905, 2024). "However, there was minimal pan-leukocytic (CD68), histiocytic (Iba-1) or hemopoietic tumor markers’ (CD45 LCA) reactivity in control tissue." (PMID 38668410, 2024). "CD68+ HLA-DR+ M1 macrophages rely on the NF-κB signaling pathway to promote tumor migration." (PMID 39040110, 2024). "Positive nuclear GSDMB expression indicated more CD68+ macrophages in the tumor microenvironment." (PMID 38711020, 2024). "Therefore, macrophages with only or predominant CD163 expression exert protumor action in the tumor as well, however, this effect is counterbalanced by expression of CD68." (PMID 38287290, 2024). "It is a well-known fact that macrophage is the most plentiful and important tumor-infiltrating immune cell type, and it would be differentiated into M2-like tumor-associated macrophage (TAM) expressing CD68+, CD163+, and CD204+ in the local milieu of OSCC stromal spaces." (PMID 38671413, 2024). "Immune cell infiltration was further explored in the U-CAN validation cohort using multiplex immunohistochemistry and multispectral imaging to detect cytotoxic T cells (CD8+), T helper 1 cells (T-bet+), T regulatory cells (FoxP3+), B cells (CD20+), and macrophages (CD68+) at the tumour front." (PMID 39613865, 2024).
tumor (continued). "Normal healthy cells (C1–C9), B cells (C32 and C33 with highest expression of CD19), T cells (C26 with highest expression of CD45), macrophage (C11 with highest expression of CD68), and cells containing G-/G+ bacteria (C12/C10), as well as 8 diverse tumor cell clusters were identified clearly." (PMID 38548720, 2024). "Similarly, in mouse tumor tissues, the expression of the panmacrophage marker CD68 was lower in the LINC00330 group than in the control group but was significantly greater in the sh-LINC00330 group." (PMID 38769475, 2024). "Univariate Cox proportional regression analysis identified various risk factors for OS in the training cohort, including tumor number, size, differentiation, MVI, AFP, GGT, CD34, CD68, CD66b, Treg/CD8, CCR4-T, CCL17-T, CCL17-I, HHLA-2, CD73-T, and CCR4 + CD73 + cells." (PMID 38914802, 2024). "Based on the results of subsequent prognostic analysis, we selected B7-H4, CD3, CD8, CD20, and CD68 for multiplex immunofluorescence staining to show more straightforwardly the differences in the tumor immune microenvironment of the primary tumor and brain metastases." (PMID 38267913, 2024). "Multiplex fluorescent immunohistochemistry (mIHC) of FABP4, C1q, and CD68 (a common surface marker of macrophages) was performed on paraffin-embedded tumor tissues, lymph nodes, distal normal lung tissues of patients with NSCLC, and the same results were obtained." (PMID 39353883, 2024). "There was a weak correlation between the PD-L1 expression on tumor cells and the infiltration of CD68+ macrophages (r = 0.2957, p = 0.0031), and a strong correlation between PD-L1 expression on interstitial cells and the infiltration of CD68+ macrophages (r = 0.8369, p < 0.0001)." (PMID 38970071, 2024). "Moreover, we stratified patients according to the median value of all estimated CD68+ macrophages in the tumor samples (M0 + M1 + M2)." (PMID 38600583, 2024). "Tumor-supporting activity is related to facilitating tumor invasion, proliferation and migration (mediated by CD204, CD206, CXCL16, stabilin-1, and RAGE), M2-like TAM polarization (by CD36, LOX-1, CXCL16, CD163, and RAGE), and tumor angiogenesis (by CD68, Dectin-1, and RAGE)." (PMID 39516356, 2024). "In addition, comparative experiments are needed to explore the interaction mechanism of bacterial presence with immune (CD45 and CD68) or tumor cells (IFI6 and ISG15) based on the existing findings of marker expression correlations." (PMID 38548720, 2024). "Within the epithelial compartment, we found highly statistically significant associations with survival for intraepithelial CD8+ T cells (including both FoxP3– and FoxP3+ subsets), PD-1+ immune cells, CD68–PD-L1+ cells (presumptive PD-L1+ tumor cells), and B cells." (PMID 39470729, 2024). "Increased numbers of CD68+/PDL1+/CD163- cells at intratumoral sites but not in tumor stroma were associated with favorable clinical outcomes." (PMID 39044824, 2024). "Thus, for MELF infiltration EEC, it is necessary to be careful in determining lymph node status, and immunohistochemical labeling of CKpan and CD68 should be performed when necessary to avoid missing isolated tumor cells and micrometastasis." (PMID 39456648, 2024). "However, we found that proinflammatory CD68+/pSTAT3+ and CD68+/HLA-DR+ macrophages were present both in the tumor and stroma of bone metastases." (PMID 38193534, 2024). "In the majority of studies, correlations of CD68 expression with the following clinicopathological parameters, histological grade, tumor size, TNM stage, lymph node status, and lymphovascular invasion, as well as with distant metastasis, recurrence and survival rates, were analyzed." (PMID 39516356, 2024). "The reason for this might be the heterogeneity of CD68+ cells across different sites of the tumor microenvironment." (PMID 38133211, 2023).
tumor (continued). "It should be noted that acetaminophen increased CD68+ macrophage tumor infiltration and led to decreased tumor size in athymic rats, thus extrapolation to the immune-competent setting may be problematic." (PMID 38299150, 2023). "Additionally, a high density of CD68-labeled macrophages in the tumor microenvironment was correlated with high infiltration of CD8 T cells and CD3 T cells, which can regulate the macrophage polarization to the M2 subtype leading to CRC metastasis." (PMID 37525217, 2023). "However, the low-grade group showed significantly more CD68+ macrophages in both the tumor and total region than the high-grade group." (PMID 38023213, 2023). "Furthermore, we found a significant increase in DAB2+, CD68+ and DAB2+ CD68+ cells in tumor associated stroma of metastatic HGSOC compared to matched primary tissues." (PMID 37815603, 2023). "For colorectal cancers, tumor-infiltrating macrophages (CD45+CD68+) expressed VISTA." (PMID 36891296, 2023). "For example, the number of CD68+ macrophages, the count of tumor-infiltrating lymphocytes, and the expression of TGF-β in different genetic levels could serve as prognostic and predictive markers." (PMID 38090481, 2023). "In this case, CD64+CD68+CD163- TAM were dominant in tumor stroma." (PMID 37691949, 2023). "Quantitative multiplexed IF targeting the PD-L1 and PD-1 protein levels, CD68 + macrophages, CD8 + T cells, FOXP3 + regulatory T cells, and CK + tumor cells was used to assess the association between the complex tumor-immune interrelations and the risk of recurrence." (PMID 36959234, 2023). "Additionally, the number of CD3+ cells in the tumor microenvironment was found to be correlated with the number of CD68+ cells, which raises the further necessity of evaluating macrophage populations." (PMID 37189554, 2023). "Expression of MMPs by cancer-associated fibroblasts and mononuclear inflammatory cells is associated with a worse prognosis in BC, and tumor-associated CD163+ and CD68+ macrophages (TAMs) in the tumor stroma are associated with higher stage and invasiveness in BC." (PMID 37046676, 2023). "However, the low-grade group showed significantly more CD68+ macrophages, including CD68+, CD68+CD163-, CD68+CD163+, CD68+PD-1-, CD68+PD-1+, CD68+PD-L1-, and CD68+PD-L1+ cells, in both the tumor and total region than the high-grade group." (PMID 38023213, 2023). "Furthermore, although CD68 is recognized as a pan-macrophage marker, low expressions of CD68 can also be found in other cell types such as fibroblasts, endothelial cells, and tumor cells." (PMID 36836239, 2023). "In addition, we found that patients with a low CD163/CD68 expression ratio within the tumor significantly benefited from adjuvant chemotherapy compared to patients with a high CD163/CD68 expression ratio within the tumor." (PMID 37208929, 2023). "High magnification images of CD68 stains were imaged and averaged over viable tumor." (PMID 37488490, 2023). "When analyzing CD68-IHC (%Area) across the tumor content groups, we also observed clear differences in CD68 expression with the lowest CD68 expression in the solid areas and higher CD68 expression in the tumor-adjacent areas (infiltration zone, p = 0.089, some tumor, p < 0.01)." (PMID 37697350, 2023). "This suggests that cases with close interaction of CD8+ and CD68+ cells in the tumor might respond better to NK cell therapy." (PMID 36694264, 2023). "Similarly, we analyzed the tumor and CD68+ cells’ local metabolite competition as a distance from CD31+ endothelial cells." (PMID 38086839, 2023). "Para-tumorous CD68+ macrophages exceeded that in tumor samples of HL group (P < 0.001)." (PMID 37215452, 2023).